MYC (MYC proto-oncogene, bHLH transcription factor)
Diseases named in the same sentence as MYC in open-access papers (continued):
Sharing a sentence is not in itself a finding about the gene and the disease.
tumor (continued). "Therefore, the regulation of GDF-15 by MYC also promotes the escape of tumor cells from macrophage attack." (PMID 40732268, 2025). "Intriguingly, single-cell RNA sequencing (scRNA-seq) identified PPARδ as a directly druggable upstream target, which integrates both starvation and tumor microenvironmental signals to modulate cellular metabolism and invasiveness via increasing the MYC/PGC1A ratio." (PMID 40607925, 2025). "Taken together, Intratumor heterogeneity (ITH) of metastasis was relatively more dynamic than that of primary samples, and MYC+ proliferative cells could play residual refractory characteristics in tumor progression." (PMID 40615564, 2025). "In summary, these results demonstrate that EVO is capable of suppressing the expression of the ASS1 protein via the Wnt/β-catenin/c-MYC signaling pathway, thereby suppressing arginine synthesis metabolism and tumor growth, while also activating the immune microenvironment of tumor cells." (PMID 41304979, 2025). "To further assess whether active PLK1 was associated with MYC or HSF1 in primary samples of patient with HGSOC, we performed IHC for active PLK1 (pT210), HSF1, and MYC using 58 tumor samples of patients with HGSOC." (PMID 39831777, 2025). "In subcutaneous tumor‐derived CTOSs, at basal MYC expression level, CTOSs showed polarity switching similar to the AP subtype and LUAD‐cell lines under different culture conditions, while MYC‐overexpressing CTOSs exhibited resistance to polarity switching like MP‐subtype CTOSs." (PMID 39899538, 2025). "While SETD8 stabilizes MYC through methylation as demonstrated in our study, this interdependence establishes a potential positive feedback loop within the SETD8/MYC axis, which may critically sustain oncogenic signaling and tumor progression in BC." (PMID 40091385, 2025). "The overactivated IFN-γ and IFN-α axes converge to drive pathological antigen presentation and reactivation of the pathways, creating a vicious cycle that sustains downstream targets (STAT, MYC, Bcl-2, Bcl-xL), facilitating tumor cell proliferation, migration, and drug resistance." (PMID 40990011, 2025). "MYC inhibition can induce tumor dormancy and promote a pluripotent‐like state." (PMID 40661135, 2025). "MYC is a proto-oncogene family that has an essential role in cell cycle regulation, differentiation, and is thought to have mostly maternal imprinting (i.e., tumor formation occurs almost exclusively through paternal transmission." (PMID 41446467, 2025). "It is highly likely, but remains to be tested, whether MYC's intrinsic ability to phase separate and/or bind RNA contributes to its oncogenic potential in a relevant tumor model." (PMID 40488968, 2025). "The MYC-RTKs axis also shields tumor cells from apoptosis and senescence." (PMID 40076599, 2025). "PLK1 inhibitors preferentially induce apoptosis of MYC-overexpressing tumor cells." (PMID 39779613, 2025). "This phenomenon suggests that targeting MYC may play a critical role in regulating cell-cell interactions, particularly interactions between tumor cells and immune cells, thereby enabling tumor cells to establish a more favorable TME." (PMID 40732268, 2025). "Compared with adjacent non-tumor tissues, MYC is overexpressed in G3 MB tumor tissues." (PMID 40229260, 2025). "Importantly, aberrant BET activity, particularly that of BRD4, has been linked to the overexpression of oncogenes such as MYC, BCL-2, and NF-κB, which drive tumor proliferation, survival, and immune evasion." (PMID 41335282, 2025). "Notably, tumor positivity for c-MYC and ALDH1A1 was associated with longer disease-specific survival, thus suggesting their role as tumor suppressors." (PMID 41463190, 2025). "Third, due to MYC’s interactions with so many distinct proteins, which are often context-dependent, the effects of indirect MYC inhibition are probably specific to certain tumor types." (PMID 40290126, 2025).
tumor (continued). "Similarly, ORC2 knockdown reinstated the combination treatment’s inhibitory effects on tumor growth and viability in MYC-overexpressing cells." (PMID 40316534, 2025). "Given the metabolic shifts induced by RR-sEVs, targeting oxidative phosphorylation or MYC-driven pathways could be an effective strategy for sensitizing tumor cells to radiation." (PMID 40568172, 2025). "MYC is known to facilitate tumor immune escape by activating Tregs." (PMID 41210882, 2025). "Additionally, pathways driving cell proliferation—such as MYC targets, the cell cycle, mTORC1 signaling, and DNA repair mechanisms—were significantly upregulated, supporting rapid tumor growth and genomic stability." (PMID 40429829, 2025). "The abnormal activation of MYC may aggravate the inflammatory response in the tumor microenvironment by enhancing DVL1 expression, and the synergistic action of NF- κ B and STAT 3 may further drive the pathological progression of SIC." (PMID 40276499, 2025). "However, in tumor cells, the overexpression or uncontrolled activation of MYC often drives tumorigenesis and progression." (PMID 40303931, 2025). "Additionally, Buguzhi, Guizhi, Mudanpi, and Fuling downregulated the “MYC targets v1” and “G2M checkpoint” gene sets, which are closely related to the inhibition of tumor cell proliferation and cell cycle progression." (PMID 41011149, 2025). "Nonetheless, the treatment model harboring MYC‐overexpressing tumor revealed that not only was there a significant decrease in local M2‐like macrophages infiltration, but there was also a notable reduction in the detection rate of CTCs and the dissemination index in the peripheral blood of mice." (PMID 39899538, 2025). "Furthermore, we found that both AhR and c‐MYC inhibition in tumor cells increased level of STAT3 phosphorylation, which was required for I3A‐induced immunogenicity." (PMID 40583248, 2025). "We demonstrate that tumor Cx31 depletion diminishes MYC-high TNBC tumor growth." (PMID 40835606, 2025). "On these grounds, there is a strong rationale to investigate whether a drug such as CBL0137 is also able to counteract MYC-mediated immune suppression and promote anti-tumor immunity." (PMID 39706891, 2025). "This hypothesis became particularly attractive when considering emerging evidence correlating MYC overexpression with the generation of an immune suppressed tumor microenvironment." (PMID 39706891, 2025). "In a nutshell, MYC regulates the expression of crucial genes by either binding or not binding to certain genes, thereby establishing an immune suppressive signature that is conserved throughout many tumor entities." (PMID 40488968, 2025). "In addition, CDK4 indirectly supports metabolic adaptation by modulating the activity of enzymes involved in lipid synthesis and nucleotide biosynthesis, pathways that are frequently co-opted by MYC to support tumor growth." (PMID 40076599, 2025). "MYC proteins orchestrate and regulate manifold processes ‐ from the nucleus to the plasma membrane of eukaryotic cells and its omnipresence in human tumors make it a tempting target for tumor therapy." (PMID 40488968, 2025). "It is unclear whether SCLC-N truly represents a subtype of SCLC with distinct outcomes and therapeutic sensitivities, or rather a snapshot from a continuum in tumor evolution driven (principally) by MYC toward an aggressive, recalcitrant disease." (PMID 40694497, 2025). "While this pro-tumorigenic axis complicates prognosis, it also hints at combinatorial strategies: targeting MYC alongside ICIs could exploit POLD1-driven immunogenicity while curbing tumor growth." (PMID 40661943, 2025). "Furthermore, cell lines obtained from such metastases retained the expression of some stemness factors (e.g., SOX2, KLF4, c-MYC) and were able to form tumorspheres in vitro, confirming the tumor stem cell behavior of these isolated subpopulations." (PMID 40806546, 2025).
tumor (continued). "Furthermore, IHC analysis of eight paired tumor and adjacent normal tissues revealed markedly elevated MYC expression in tumor tissues." (PMID 40740861, 2025). "However, the patient tumor exhibited variability in the form of MYC amplification, with some instances detected as extrachromosomal DNA (ecDNA) and others as a homogeneously staining region (HSR)." (PMID 39416100, 2025). "MYC is also widely acknowledged for its role in mediating the immune evasion of tumor cells." (PMID 40732268, 2025). "Additionally, MYC is frequently dysregulated in lung, colorectal, and pancreatic cancers, where its aberrant expression correlates with tumor aggressiveness and treatment resistance." (PMID 40365020, 2025). "Previous investigations have indicated that the phenotypic effects of FAM111B encompass energy metabolism and cellular adaptability, actions congruent with established functions of MYC in energy metabolism, tumor maintenance, proliferative inhibition, senescence, and apoptosis." (PMID 40781291, 2025). "Together, these findings suggest that FMR1 may influence tumor progression through multiple downstream effectors; however, we focused on the c-MYC pathway as the downstream regulatory axis of greatest interest for further investigation." (PMID 41184982, 2025). "Moreover, compared to the oe-NCL + oe-NC + oe-NC group, the oe-NCL + oe-MYC + oe-NC group showed decreased tumor cell proliferation, increased apoptosis, significantly increased permeability, and a notable decrease in the invasive spread capacity of spheroids." (PMID 40346484, 2025). "This discrepancy suggests that the unique tumor microenvironment in vivo may play a critical role in facilitating MYC addiction in cancer cells." (PMID 40732268, 2025). "Thus, PRMT3’s role in stabilizing c-MYC creates a feedback loop that not only promotes tumor growth but also inhibits effective anti-tumor immune responses." (PMID 41583428, 2025). "Similar arguments could explain the heterogeneity observed among Tet-MYC and different B/Y/N tumor types." (PMID 41440033, 2025). "In these studies, it has also been indicated that downregulation of MYC expression may enhance sensitivity of tumor cells to cisplatin." (PMID 39031286, 2024). "In MYC-induced tumor formation screens, many oncogenes were found to cooperate with MYC." (PMID 37450923, 2024). "For instance, inhibiting a MYC-SL target may also have beneficial on-target but off-tumor effects on the tumor microenvironment." (PMID 38302473, 2024). "Studies have indicated that BRD7 often acts as a tumor suppressor, whereas BRD9 is a pro-oncogenic protein, the mechanism of which is potentially linked with the STAT5 signaling pathway and the expression of MYC in hematological tumors." (PMID 39580422, 2024). "These pathways were also the top five enriched pathways in the R group of the eight internal HGSOC samples: oxidative phosphorylation in the tumor and stromal regions, TNF-α signaling via NF-κ in the tumor region, G2/M checkpoint, E2F target, and MYC target V1 in the stromal region." (PMID 39135097, 2024). "Although SPT5 is an essential protein, its interaction with MYC could indicate that tumor cells are more dependent on the full function of SPT5 than untransformed cells." (PMID 37935464, 2024). "Interestingly, MYC has been found to be crucial also in the crosstalk cancer-stroma and in the regulation of the tumor microenvironment of several tumors, including OS." (PMID 39596100, 2024).
tumor (continued). "Understanding dysregulated protein synthesis in MYC-driven oncogenesis is crucial for developing targeted therapeutic interventions that leverage the inherent vulnerabilities of these pathways in the context of tumor development." (PMID 39574899, 2024). "MYC and MDM2 are involved in inflammation and fibrosis and are associated with tumor proliferation." (PMID 39618816, 2024). "Similarly, Insulin-like growth factor-2 mRNA-binding proteins (IGF2BP1/2/3) have been found to be overexpressed in AML, and to regulate the stability of specific mRNAs, including MYC, in an m6A-dependent manner to promote tumor progression." (PMID 39085650, 2024). "Furthermore, studies have reported that FGFR3 and MYC overexpression led to an increase in Tregs, inducing an immunosuppressive tumor microenvironment (TME), while ERBB2 overexpression was linked to a decrease in Tregs." (PMID 39410541, 2024). "Altogether, we suggest a new mechanism in which downregulation of tumor suppressive hsa-miR-150-5p, sequestered by hsa-circ-0001955, may contribute to MYC upregulation in CRC patients and its consequences." (PMID 38167453, 2024). "Tumor cells with MYC overexpression exhibit cell cycle dysregulation, which may make their proliferation particularly sensitive to the inhibition of an important regulator of cell cycle progression - cyclin-dependent kinase (CDK)." (PMID 38638876, 2024). "We propose that our dose-titrating systems can model a non-linear OIS spectrum, including senescence intermediates such as slow-cycling (RPE1 cells) and immune-resistant tumour-initiating states (mouse livers), both characterized by increased progenitor features and a reduced MYC signature." (PMID 39112713, 2024). "Recent studies found that ACC tumours could be categorized into two main subtypes, in which ACC-I exhibited MYC overexpression and NOTCH mutation with poor prognosis, and ACC-II exhibited P63 overexpression and RTK upregulation with improved prognosis." (PMID 39258959, 2024). "Furthermore, the administration of lupeol to a nude mouse model with implanted Mel 928 cells demonstrated a substantial reduction in tumor growth and a decreased expression of c-MYC and CCND1." (PMID 39684513, 2024). "Over 4 decades of research and some 10,000 publications linking it to tumorigenesis (by searching PubMed for “MYC oncogene”) have led to MYC becoming a most-wanted target for the treatment of cancer, where many of MYC’s physiological functions become co-opted for tumour initiation and maintenance." (PMID 38510176, 2024). "PTEN acts as a negative regulator for the VEGF signaling pathway and MYC-driven tumor genesis." (PMID 38535330, 2024). "Moreover, the combination of CDK4/6i and MYC-degrading molecule A80.2HCl shows an additive effect on killing tumor cells both in vitro and in vivo." (PMID 38424044, 2024). "In CAM453, a duplication event (chr8:126694685-130657526) was identified in both the tumor and organoid (CN 0.4 and 108.5 respectively) using GRIDSS-LINX29, suggesting that the amplicon was present at a low CN in the tumor and clones harboring the MYC ecDNA expanded in the derived organoid." (PMID 38744814, 2024).
tumor (continued). "In MYC-driven small cell lung cancer, tumors rely heavily on the arginine synthesis pathway, and depleting arginine using pegylated arginine deiminase can significantly inhibit tumor growth and improve survival rates in mouse tumor models." (PMID 39744129, 2024). "Indeed, let-7 inhibits LC tumor growth by targeting c-MYC, KRAS and HMGA2, binds to DICER, i.e., a RNAase which processes miRNAs, and induces cell autophagy in LC." (PMID 38245882, 2024). "The hallmark oncogene MYC drives the progression of most tumours, but direct inhibition of MYC by a small-molecule drug has not reached clinical testing." (PMID 38821858, 2024). "Thus, our genome wide CRISPR-screen served as a powerful approach to determine specific MYC-SL genes and pathways as well as genes with anti-tumor suppressive function." (PMID 38302473, 2024). "The MYCBP/c-MYC pathway plays an important role in tumor development." (PMID 38570856, 2024). "We reanalysed RNA-seq datasets derived from this mouse model and found a lower level of MYC and E2F targets in TICs than in the rest of the tumour cells, a trend that was also unique to MYC among the downstream transcription factors of the RAS–MAPK pathway examined." (PMID 39112713, 2024). "MYC was aberrantly expressed in both tumor initiation and maintenance." (PMID 38566153, 2024). "Furthermore, they showed that IL-6 promoted engraftment and dissemination of IL-6R expressing tumour cells in a mouse model, as well as promotion of MYC-driven lymphomagenesis." (PMID 38633747, 2024). "Indeed, we found that MLN0128 treatment effectively suppressed c-MYC/MCL1/RictorKOTsc2KO tumor growth, and it was more effective than the p70S6K/RPS6 inhibitor everolimus." (PMID 39325536, 2024). "We therefore hypothesized that targeting CDK9 may turn off MYC-driven tumor survival and drug resistance." (PMID 38886769, 2024). "One (c-MYC P0 5′UTR) behaves as a tumor suppressor and the other (VEGF 5′UTR) as an oncogene." (PMID 39054345, 2024). "The c-MYC/Cre mice displayed a higher tumor burden than did the c-MYC/pCMV control mice." (PMID 39325536, 2024). "Transactivation of BUB1 by MYB may promote tumour development, since overexpression of BUB1 cause hyper‐activation of Aurora B activity, aneuploidy, and spontaneous and MYC‐induced transformation in a transgenic mouse model." (PMID 38112379, 2024). "Recently, various drug-based approaches have been proposed to target MYC and impede tumor growth." (PMID 38383388, 2024). "Additionally, AEG-1 was found to be associated with various biological processes, such as angiogenesis, apoptosis, ECM-related genes, EMT markers, G2/M checkpoints, immune response, MYC markers, tumor proliferation, and TGF-β signaling." (PMID 39483471, 2024). "SNAP25 influences tumor progression by activating c-MYC through the MEK/ERK pathway." (PMID 39430761, 2024). "In addition to downregulating c-MYC and directly inhibiting the proliferation of tumor cells, the BRD4 inhibitor NHWD-870 blocks the proliferation of tumor-associated macrophages (TAMs) through various mechanisms." (PMID 38811964, 2024). "Interactions of WDR5 with other proteins such as MYC may also play a role in promoting tumor growth." (PMID 38744853, 2024). "Interestingly MYC and RB1 were the most frequently altered genes that were associated significantly with a lower abundance of CD8+ T-cell infiltrates across different tumor types." (PMID 38398121, 2024). "Nevertheless, the fact that in our study the expression of anti-apoptotic BCL-2 was not restored in repaired subclones suggests that enhanced ADCC after MYC modulation is not solely influenced by BCL-2, highlighting the multifaceted mechanisms of MYC to escape from anti-tumor immune responses." (PMID 39596160, 2024).